LGI1 (leucine rich glioma inactivated 1)
Diseases named in the same sentence as LGI1 in open-access papers (continued):
Sharing a sentence is not in itself a finding about the gene and the disease.
status epilepticus (6 papers, 2020 to 2025). Status epilepticus is defined as a continuous seizure lasting more than 30 min, or two or more seizures without full recovery of consciousness between any of them. "Compared with those in the other two groups, patients in the GABABR group were more likely to experience status epilepticus (p=0.01), and patients in the LGI1 group were more prone to abnormal brain MRI results (p=0.049)." (PMID 35281052, 2022). "Here, we present three patients who were admitted with recalcitrant status epilepticus and demonstrated serum antibodies against NMDAR, LGI1, or VGCC using a cell-based assay." (PMID 32655958, 2020). "The lateralized periodic discharges observed in this case have been previously reported in only one of 151 cases of anti-LGI1 LE, suggesting that the patient was in the ictal-interictal continuum of non-convulsive status epilepticus." (PMID 40007925, 2025). "Here, we present a rare and unusually severe case of anti-LGI1 LE characterized by late-onset and disabling symptoms, including an ictal-interictal continuum of non-convulsive status epilepticus." (PMID 40007925, 2025).
Anxiety (5 papers, 2019 to 2025). Intense feelings of nervousness, tension, or panic often arise in response to interpersonal stresses. "Anti-LGI1 mAb-infused mice showed an anxiety-like, hypoactive phenotype." (PMID 39984135, 2025).
encephalomyelitis (5 papers, 2014 to 2025). Inflammation of the brain and the spinal cord. "Furthermore, LGI1 antibodies were detected in a glutamic acid decarboxylase antibody-positive patient suffering from progressive encephalomyelitis with rigidity and myoclonus (PERM)." (PMID 24950993, 2014). "Patient #1 presented as LGI1- and GAD-IgG positive immune-mediated encephalitis, patient #2 was diagnosed with MOG-IgG positive encephalomyelitis, and patient #3 had chronic inflammatory polyneuropathy associated with SSA(Ro)-IgG positive Sjögren’s syndrome." (PMID 33875720, 2021).
Hyperhidrosis (5 papers, 2021 to 2024). Abnormal excessive perspiration (sweating) despite the lack of appropriate stimuli like hot and humid weather. "When paroxysmal unilateral symptoms, such as weakness of limbs, convulsions, and hyperhidrosis, are noticed, it is essential for patients to undergo LGI1 antibody testing for accurate diagnosis and treatment of this unusual disease." (PMID 37304289, 2023).
neuroblastoma (5 papers, 2009 to 2022). Neuroblastoma (NB) is the most common solid, extracranial childhood tumor. "Previous works show that Lgi1 inhibits the proliferation and causes the apoptosis of neuroblastoma cells, which might be mediated by altered AKT and ERK (extracellular-signal-regulated kinase) signaling However, the roles of Lgi1 in oncogenesis still remain quite unclear." (PMID 30034322, 2018). "The ability of LGI1 to suppressor growth of neuroblastoma cells was suggested by the results of LGI1 overexpression, which was shown to impair proliferation and to induce apoptosis through the inhibition of the PI3K/AKT pathway." (PMID 20111625, 2009). "In support to this proposal were the findings that overexpression of LGI1 in neuroblastoma cells inhibited proliferation and induced apoptosis." (PMID 20111625, 2009). "In cancer, LGI1 has been shown to function as a tumour suppressor gene for glioblastoma and neuroblastoma, and we have previously reported LGI1-targeted inhibition of cell migration in ER-positive endocrine-resistant breast cancer cells mediating distant metastatic competency." (PMID 33208158, 2020). "In cancer, a tumour suppressor role for LGI1 has been described in glioblastoma and neuroblastoma, and it has been shown that LGI1 may play a role in impairing proliferation and survival in HeLa cells." (PMID 33208158, 2020). "The aim of this study was to establish whether LGI1 was capable to suppress growth of cancer cells different from glioblastoma and neuroblastoma." (PMID 20111625, 2009). "None were positive for LGI1/CASPR2 antibodies (Abs), 2/25 were positive for serum anti‐NMDAR Abs, and 2/15 positive for anti‐Hu Abs; one died from relapsing neuroblastoma." (PMID 35015932, 2022).
Atrophy (4 papers, 2017 to 2024). Any weakening or degeneration, especially through lack of use. "report that chronic LGI1 antibody VGKC-complex LE is associated with focal CA3 atrophy on 7.0-Tesla neuroimaging and autobiographical episodic amnesia." (PMID 28369215, 2017). "Other studies on patients with selective CA3 atrophy caused by leucine-rich glycine-inactivate-1 antibody-complex limbic encephalitis (LGI1-antibody-complex LE) have shown significant associations with CA3 atrophy and impaired recent and remote autobiographical episodic memory." (PMID 37900611, 2023).
depression (4 papers, 2021 to 2025). "In addition, depression potentially leads to downregulated LGI1." (PMID 35003396, 2021).
Epileptic encephalopathy (4 papers, 2021 to 2025). A condition in which epileptiform abnormalities are believed to contribute to the progressive disturbance in cerebral function. "Pathogenic variants in A Disintegrin And Metalloproteinase (ADAM) 22, the postsynaptic cell membrane receptor for the glycoprotein leucine-rich repeat glioma-inactivated protein 1 (LGI1), have been recently associated with recessive developmental and epileptic encephalopathy." (PMID 35373813, 2022).
Generalized tonic clonic seizures (4 papers, 2020 to 2025). "In this case, focal impaired awareness seizures and tonic-clonic seizures, both common in anti-LGI1 LE, were observed." (PMID 40007925, 2025).
glioblastoma (4 papers, 2009 to 2025). The most malignant astrocytic tumor (WHO grade IV). "The second most cited literature, published by Meizan Lai in LANCET NEUROLOGY, further elucidates that LGI1, initially isolated from glioblastoma cell lines, is associated with tumor aggressiveness and may function as a potential metastasis suppressor gene." (PMID 40535121, 2025). "Regarding the LGI1 protein, previous research has demonstrated its inhibitory effects on the formation and progression of glioblastoma, although it requires ligands to exhibit biological activity." (PMID 40535121, 2025). "In order to further determine the correlation between Lgi1 and myelin proteins, we measured their expressions in glioblastomas." (PMID 30034322, 2018). "The LGI1 gene was suggested to function as tumor suppressor for its ability to reduce malignant features of glioblastoma cells." (PMID 20111625, 2009). "For instance, LGI1 (leucine-rich glioma inactivated protein 1), a component protein of the voltage-gated potassium channel (VGKC), plays a regulatory role in influencing the aggressiveness of glioblastoma." (PMID 40535121, 2025).
lung carcinoma (4 papers, 2020 to 2025). "Four anti‐LGI1 patients had tumors: 1 patient had lung cancer, 1 colon adenocarcinoma, 1 renal cell carcinoma, and 1 rectal adenocarcinoma." (PMID 32783406, 2020).
Myoclonus (4 papers, 2019 to 2025). Very brief, involuntary random muscular contractions occurring at rest, in response to sensory stimuli, or accompanying voluntary movements. "We selected the 10 most frequently observed semiologies in LGI1-Ab-E cats, replacing head nodding (as it showed overlap with the head nodding/turning/version category and a lower kappa (0.123 compared to 0.161)) with myoclonus." (PMID 39984138, 2025).
neuromyelitis optica spectrum disorder (4 papers, 2020 to 2025). "There have been a series of case reports documenting the use of efgartigimod in Guillain–Barré syndrome (GBS), Neuromyelitis Optica Spectrum Disorder (NMOSD), anti-leucine-rich, glioma inactivated 1 (LGI1) antibody-associated autoimmune encephalitis (AE) and other disorders." (PMID 40470493, 2025).
breast carcinoma (3 papers, 2020 to 2021). "LGI1, a tumour suppressor, inhibits the growth and metastasis of breast cancer by target binding to ADAM23/AMAM22." (PMID 35003396, 2021). "We have previously reported LGI1-induced inhibition of cell migration in endocrine-resistant breast cancer cells." (PMID 33208158, 2020). "Given the elevated levels of ADAM22 in breast cancer brain metastatic tumours and the efficacy of LGI1MIM in inhibiting early metastatic events, we evaluated the potential of LGI1/ADAM22 complex as a new therapeutic strategy in breast cancer-BBB model systems." (PMID 33208158, 2020).
Dyskinesia (3 papers, 2019 to 2023). A movement disorder which consists of effects including diminished voluntary movements and the presence of involuntary movements. "Dyskinesia was the commonest movement disorder in anti-NMDA antibody mediated AE and faciobrachial dystonic seizures were most frequent in anti-LGI1 antibody mediated AE." (PMID 37545714, 2023).
epileptic syndromes (3 papers, 2009 to 2022). "Mutations of non-ion channel genes like leucine-rich, glioma inactivated 1 gene (LGI1) or Aristaless related homeobox gene (ARX) may also cause epilepsy syndromes." (PMID 19333415, 2009).
melanoma (3 papers, 2010 to 2025). A malignant, usually aggressive tumor composed of atypical, neoplastic melanocytes. "Four (9%) had a new or recurrent malignancy discovered within 2 years of their LGI1‐AE diagnosis, including melanoma (n = 2), prostate adenocarcinoma (n = 1), and appendiceal mucinous carcinoma (n = 1)." (PMID 40781580, 2025). "Three of our patients had a history of cancers, none of which were active at the time of LGI1 encephalitis (prostate cancer and melanoma, prostate cancer and basal cell carcinoma of the skin, and squamous cell carcinoma of the skin)." (PMID 36304459, 2022).
absence seizures (2 papers, 2025). "The residues GLU81, ILE61, ILE82, PHE79, SER60, SER83 and SER86 have been previously reported to be involved in the interaction between ethosuximide and LGI1 complex, which contributes to the treatment of absence seizures." (PMID 41386826, 2025). "Similarly, NMDAR‐ but not LGI1‐IgG‐infused Wistar rats exhibited increased susceptibility to PTZ‐induced absence seizures compared to healthy control group." (PMID 40542581, 2025). "However, the roles of LGI1 and NMDAR dysfunction in the pathophysiology of absence seizures remain unclear." (PMID 40542581, 2025).
brain tumors (2 papers, 2015 to 2024). "It is found that the later gene, LGI1, is predominantly expressed in neural tissues and its expression is reduced in low grade brain tumors and significantly reduced or absent in malignant gliomas." (PMID 25794193, 2015).
cardiac arrhythmia (2 papers, 2017 to 2022). Any disturbances of the normal rhythmic beating of the heart or MYOCARDIAL CONTRACTION. "However, as all cardiac dysrhythmias in our study were not temporally related to the seizures an alternative pathophysiology such as a potential direct role of LGI1 IgG on cardiac myocytes is possible." (PMID 36304459, 2022).
delirium (2 papers, 2024 to 2025). A disorder characterized by confusion; inattentiveness; disorientation; illusions; hallucinations; agitation; and in some instances autonomic nervous system overactivity. "On the other hand, the syndrome of inappropriate antidiuretic hormone secretion, delirium, mood changes, and myoclonus typically arise in patients with anti-LGI1 antibodies." (PMID 38779241, 2024).
developmental and epileptic encephalopathy (2 papers, 2023 to 2025). An epilepsy associated with developmental impairment that may be due to either the underlying etiology or the superimposed epileptic activity, or both. "Pathogenic variants of ADAM22 affecting either its biosynthesis and/or its interactions with either LGI1 and/or PSD-95 have been recently identified in individuals with developmental and epileptic encephalopathy." (PMID 37953841, 2023).
Guillain-Barre syndrome (2 papers, 2016 to 2022). A spectrum of rare post-infectious neuropathies that usually occur in otherwise healthy patients. "Sporadic cases of neurological effects after vaccination for Anti-LGI1 Encephalitis, Guillain-Barre syndrome (GBS), and Neuralgic amyotrophy have been reported, highlighting that the vaccine may influence CNS." (PMID 36558835, 2022).
Lambert-Eaton myasthenic syndrome (2 papers, 2018 to 2022). Lambert-Eaton myasthenic syndrome (LEMS) is an autoimmune, presynaptic disorder of neuromuscular transmission characterized by fluctuating muscle weakness and autonomic dysfunction frequently associated with small-cell lung cancer (SCLC). "Third, the HLA similarities between tumour and non-tumour LGI1-antibody cases suggests the absence of a unique paraneoplastic signature, in contrast to Lambert-Eaton myasthenic syndrome." (PMID 29788256, 2018).
malignant glioma (2 papers, 2015 to 2022). A grade III or grade IV glioma arising from the central nervous system. "A tumor and metastasis protein LGI1 was reduced in GBM samples; this is consistent with significant reduction, inactivation, or absence of LGI1 observed in malignant gliomas, making it a strong tumor suppressor gene candidate involved in the malignant progression." (PMID 35202840, 2022).
myocardial ischemia (2 papers, 2022 to 2025). A disorder of cardiac function caused by insufficient blood flow to the muscle tissue of the heart. "Pathology showed no significant coronary disease or evidence of myocardial ischemia, further highlighting the importance of understanding the rare but potential fatal cardiac dysfunction in LGI1 AE." (PMID 36304459, 2022).
paraneoplastic neurological syndromes (2 papers, 2018 to 2025). "According to the 2021 update of the diagnostic criteria for paraneoplastic neurological syndromes (PNSs), LGI1 antibodies are classified as low risk for paraneoplastic association." (PMID 40407616, 2025). "Perhaps this implies tumours in patients with LGI1 antibodies largely reflect the age-matched background rate, rather than a distinct immune mechanism, although a paucity of tumours classically associated with paraneoplastic neurological syndromes may limit our interpretation." (PMID 29788256, 2018).
Acute encephalopathy (1 paper, 2021). "Therefore, it is important to highlight that FAMS can also serve as a rare diagnostic clue for acute encephalopathy, such as anti‐LGI1 AE." (PMID 34291554, 2021).
Allergy (1 paper, 2023). An allergy is an immune response or reaction to substances that are usually not harmful. "With CBZ for anti-LGI1 AE, the cause of allergy may be related to specific pro-immunogenic human leukocyte antigen (HLA) types and increased CBZ use; further study is needed to elucidate the exact causes of these adverse effects." (PMID 37034075, 2023).
Bradycardia (1 paper, 2022). A slower than normal heart rate (in adults, slower than 60 beats per minute). "In this study, we described a cohort of LGI1-IgG seropositive patients who had bradycardia at presentation." (PMID 36304459, 2022).
central nervous system lymphoma (1 paper, 2018). "Here, we show that incipient primary central nervous system lymphoma can closely resemble limbic encephalitis including positive testing for anti-LGI1 antibodies illustrating the need for thorough interpretation of initial laboratory and radiologic findings and tight follow-up examinations." (PMID 30147672, 2018).
esophageal squamous cell carcinoma (1 paper, 2019). Esophageal squamous cell carcinoma (ESCC) is a type of esophageal carcinoma (EC) that can affect any part of the esophagus, but is usually located in the upper or middle third. "The leucine-rich glioma inactivated 1 (LGI1) gene is a putative suppressor of metastasis and, when downregulated, was found to stimulate esophageal squamous cell carcinoma metastasis." (PMID 31892232, 2019).
esophageal tumors (1 paper, 2009). "Further support to the tumor suppressor function of LGI1 was provided by a comprehensive study on malignant esophageal tumors (Barrett's-related adenocarcinomas) showing that expression of LGI1 was consistently downregulated." (PMID 20111625, 2009).
familial temporal epilepsy (1 paper, 2018). "Human LGI1 gene mutation induces autosomal dominant partial epilepsy with auditory features (ADPEAF), a rare form of familial temporal epilepsy." (PMID 30253786, 2018).
generalized epilepsy (1 paper, 2019). Epilepsy that is characterized by generalized seizure types and may have typical interictal and/or ictal EEG findings that accompany generalized seizure types (for example generalized spike-wave). "They found that LGI1 loss (LGI1-/-) in homozygote mice induces lethal generalized epilepsy, while in heterozygote ones (LGI1+/-), this leads to a decrease in seizure thresholds." (PMID 31540204, 2019).
Hypokalemia (1 paper, 2022). An abnormally decreased potassium concentration in the blood. "Anti-LGI1 AE with hypokalemia has been rarely reported, and, to the best of our knowledge, there is only 3 cases documented until date." (PMID 36316880, 2022). "The 65-year-old female, with onset, mainly manifested facial-brachial dystonia episodes (FBDS), unresponsive, refractory hypokalemia, abnormal diffusion weighted imaging, MRI and electroencephalography, and positive anti-LGI1 and anti-mGluR5 in serum, positive anti-LGI1 in CSF." (PMID 36316880, 2022).
listeriosis (1 paper, 2017). A bacterial infection caused by Listeria monocytogenes. "LGI1 is a Listeria 50 kb genomic island that was first identified in Canadian CC8 isolates associated with a large 2008 listeriosis outbreak involving contaminated deli meats and resulting in 22 fatalities." (PMID 28337186, 2017).
metastatic disease (1 paper, 2020). "Moreover, targeting ADAM22 with LGI1 induced consistent reductions in micro-metastatic disease burden in the brain." (PMID 33208158, 2020).
migraine headache (1 paper, 2025). "Twenty-one LGI1 AE patients were enrolled from October 2018 to April 2024, and 16 migraine headache patients (56.3% male; average age: 58 years) served as non-inflammatory controls." (PMID 40470500, 2025).
Mydriasis (1 paper, 2025). Abnormal dilatation of the iris. "Resultant odds ratios to predict LGI1-Ab-E were 6.65 (orofacial automatisms and mydriasis) and 9 (temporal lobe origin; Supplementary Results 4A-C)." (PMID 39984138, 2025). "Orofacial automatisms, mydriasis and temporal lobe localisation were predictive semiological features of feline LGI1-Ab-E." (PMID 39984138, 2025). "The top four features observed in LGI1-Ab-E cats were orofacial automatisms (88/120, 73 % of observations), salivation (87/120, 73 % of observations), reduced awareness (81/120, 68 % of observations), and mydriasis (79/120, 66 % of observations)." (PMID 39984138, 2025). "Compared to LGI1-antibody-negative cats, orofacial automatisms (73 % vs. 47 % (26/55), pcorr = 0.024), salivation (73 % vs. 42 % (23/55), pcorr = 0.004), and mydriasis (66 % vs. 35 % (19/55), pcorr = 0.004) were all significantly enriched in the antibody-positive group." (PMID 39984138, 2025).
neuropathic pain (1 paper, 2025). Chronic pain caused by damage to nerve fibers. "In summary, we find that LGI1, the target of autoantibodies from neuropathic pain patients, plays a previously unrecognized role in regulating pain sensitivity." (PMID 39301592, 2025). "Leucine-rich, glioma inactivated 1 (LGI1) is a secreted protein known to regulate excitability within the nervous system and is the target of autoantibodies from neuropathic pain patients." (PMID 39301592, 2025).
oesophageal cancer (1 paper, 2021). "We hypothesized that, in the microenvironment of oesophageal cancer tissues, a depressive state would upregulate ADAM23 by downregulating LGI1 expression." (PMID 35003396, 2021).
poisoning (1 paper, 2021). A condition or physical state produced by the ingestion, injection, inhalation of or exposure to a deleterious agent. "From our experience, acquired neurosis syndrome caused by mercury poisoning is effectively cured through mercury removal, and hormone therapy may not be beneficial regardless of LGI1 and CASPR2 antibody positivity; however, further clinical observation is needed." (PMID 34397926, 2021).